TRPV1 (transient receptor potential cation channel subfamily V member 1)
Diseases named in the same sentence as TRPV1 in open-access papers (continued):
Sharing a sentence is not in itself a finding about the gene and the disease.
colitis (continued). "They claimed that CPZ activates TRPA1 in DRG neurons and the rectal administration of CPZ systemically desensitizes TRPA1/TRPV1 expressing peptidergic sensory neurons and attenuates pain and DSS-induced colitis in mice." (PMID 36076974, 2022). "Though CPZ has been employed as a strategy to ameliorate colitis related pain, its physiological effects on gut health and involvement of its key targets (TRPA1/TRPV1 sensory neurons) still remains elusive." (PMID 36076974, 2022). "Collectively, our data provide evidence of a direct TRPV1+ neuron-microglia interaction in colitis pain and suggest that restraining P2RY12 signaling in microglia, via chronic intervention on TRPV1+ neurons, will prevent VHS, despite colitis." (PMID 34954381, 2022). "Previous data showed that capsaicin, a TRPV1 agonist, attenuated severe combined immunodeficiency (SCID) T-cell transfer colitis, suggesting that the TRPV1 signaling plays a role in capsaicin-mediated attenuation of colitis." (PMID 35634308, 2022). "Previous study demonstrated that colonic inflammation triggers the release of pro‐inflammatory neuropeptides SP and CGRP in the urinary bladder via activation of TRPV1 signaling mechanisms enunciating the neurogenic nature of pelvic organ cross‐sensitization." (PMID 34136194, 2021). "Whilst considering the highly co-expressive nature of TRPV1 and TRPA1 in colonic afferents, it is interesting to shed light on the interaction between TRPV1 and TRPA1 in colitis." (PMID 32153564, 2020). "Because a systemic mutation of the TRPV1 model was used in this study, we could not exclude the possible roles of TRPV1 overactivation in other cell types affecting DC activation and Th17 responses during colitis." (PMID 33251043, 2020). "We therefore conclude that it is primarily the function of TRPA1 which, relative to TRPV1, is upregulated in DRG neurons under conditions of colitis, although the somatic vs. visceral projection of TRPA1-hyperresponsive DRG neurons awaits to be analyzed." (PMID 32451393, 2020). "Recent data pointed that TLR4-knockout mice showed a less inflammatory infiltration and a decreased expression of TRPV1 in TNBS-induced colitis, indicating one possible function of TLR4 for mediating TRPV1 signaling under inflammatory conditions." (PMID 32153564, 2020). "On the contrary, acute stimulation of sensory neurons by capsaicin, a known TRPV1 agonist, ameliorated disease symptoms in TNB-colitis in rats." (PMID 26635804, 2015). "However, 5-ASA does not inhibit direct TRPV1-mediated colitis caused by intraluminal capsaicin." (PMID 25045574, 2014). "Mice lacking TRPV1 develop significantly less oesophagitis after acid exposure compared with TRPV1+/+ mice, whilst administration of a TRPV1 antagonist before or after intracolonic TNBS administration significantly reduces colitis severity." (PMID 27713376, 2010). "Another study demonstrated chronic effects of SP on colonic primary afferents, which could sensitize TRPV1 and lead to persistent abdominal pain following acute inflammation in a mouse model of DSS colitis." (PMID 38731999, 2024). "TRPV1 and TRPV2 expression in the distal colon, dorsal root ganglion (DRG) and nodose ganglion (NG) was significantly increased in a rat model of TNBS-induced colitis." (PMID 38731999, 2024). "In addition, capsaicin can activate TRPV1 channels and has been shown to decrease DSS-induced colitis in rats when delivered subcutaneously." (PMID 37623246, 2023). "TRPV1 expressed in CD4+ T-cells is involved in the activation and differentiation of T-cells into Th1 effector cells, inducing an inflammatory response in the murine model of colitis." (PMID 37371563, 2023). "Overall, the gene expression changes detected in the vehicle-treated mice exposed to DSS were similar to those reported in the first experiment, with a tendency for a general downregulation during colitis, although in this case, statistical significance was only reached for NGF and TRPV1." (PMID 37893131, 2023).
colitis (continued). "Importantly, TNBS treatment enhanced TLR4 and TRPV1 coexpression in primary afferents including the trigeminal sensory neurons and DGR neurons of colitis mice." (PMID 36910013, 2023). "Our results suggest that chemogenetic inhibition of TRPV1+ neurons is not sufficient to reduce DSS-induced colitis, whereas CNO stimulation induces neurogenic inflammation in the colon, highlighted by TNF-α, IL-1β, or IL-6 upregulation." (PMID 34954381, 2022). "Within the lumbosacral spinal cord, an overall up‐regulation of anti‐nociceptive‐related markers (p < 0.05 for CB1, CB2, and MOR vs. control) and a down‐regulation of pro‐nociceptive‐related markers (p < 0.05 for TRPV1 and 3 and Ramp1 vs. control) was detected following DSS‐induced colitis." (PMID 36239298, 2022). "Our results indicate that chemogenetic activation of TRPV1+ visceral neurons, in the absence of colitis, is sufficient to induce microglia reactivity and VHS." (PMID 34954381, 2022). "TRPV1 agonists (capsaicin, resiniferatoxin, SA13353), may induce an anti-inflammatory effect during colitis inflammation." (PMID 35003109, 2021). "Similarly, the levels of TRPV1 and TRPA1 messenger RNA (mRNA) in mice were upregulated in mustard oil (MO)-induced colitis within 6 h but decreased 24- and 72-h after MO-injection." (PMID 32153564, 2020). "Furthermore, during DSS colitis the proportion of DRG neurons expressing TRPV1, and their relative TRPV1 mRNA levels increase with a subsequently elevated release of sensory neuropeptides, such as calcitonin gene-related peptide (CGRP) and substance P (SP)." (PMID 30935063, 2019). "Moreover, both intraperitoneal and intrathecal administrations of TRPV1 and TRPA1 antagonists exerted analgesic actions in rat colitis models highlighting central nervous system mechanisms." (PMID 30935063, 2019). "Trpv1-deficiency did not affect disease severity, only prevented chronic pain development during the recovery phase of DSS-induced colitis." (PMID 30935063, 2019). "However, they described that TRPV1 and TRPA1 gene deletion decreased colitis severity and the upregulation of SP-positive nerve fibers without influencing protective CGRP-positive nerves." (PMID 30935063, 2019). "The findings of the present study demonstrated that there is a differential gene and protein expression of TRPV1 in UC patients compared to normal controls without colonic inflammation." (PMID 30150894, 2018). "Nicotinic cholinergic receptors tonically protect the colon against inflammation and nicotine inhibits toxin A colitis but not ileitis in rats in part by inhibition of toxin A-induced activation of TRPV1 by endogenous TRPV1 agonists such as LTB4." (PMID 26881175, 2016). "In this study we show that TRPA1 agonism, rather than TRPV1 inhibition, in colonic sensory neurons is the key initial step in colitis protection by CPZ enemas." (PMID 27356469, 2016). "Nicotinic cholinergic receptors tonically protect the colon against inflammation and nicotine inhibits toxin A colitis but not toxin A ileitis in rats in part by inhibition of toxin A-induced activation of TRPV1 by endogenous TRPV1 agonists such as LTB4." (PMID 26881175, 2016). "TRPV1 itself does not appear to play a role in either DSS-induced colitis or trinitrobenzene-sulfonic-acid (TNBS)-induced colitis as these models are not altered in the TRPV1 KO mouse." (PMID 25640188, 2015). "On the other hand, the contribution of TRPV1 in gut inflammation is still controversial, as it was shown that disease severity was reduced in TRPV1 KO mice in model of DSS colitis, suggesting that TRPV1 activation may enhances inflammation." (PMID 26635804, 2015). "If 5-ASA blocks toxin A colitis by inhibiting the generation of an endogenous TRPV1 agonist such as LTB4, we reasoned that 5-ASA pretreatment should not inhibit colitis caused by an agent that directly stimulates TRPV1." (PMID 25045574, 2014).
colitis (continued). "We previously demonstrated that TRPV1 activation plays a role in toxin A-induced inflammation in the rat ileum but the role of TRPV1 has not been examined in toxin A-induced colitis." (PMID 25045574, 2014). "The intermicturition interval in TRPV1−/− mice was increased along with the number of non-voiding contractions at the baseline, and the effects of experimental colitis on bladder capacity and voided volume were diminished in comparison to WT littermates." (PMID 23305398, 2013). "In the present study, we established that the absence of TRPV1 did not affect the severity of TNBS-induced colitis in transgenic mice." (PMID 23305398, 2013). "In contrast, colonic inflammation did not alter the expression level of TRPV1 in the urinary bladder." (PMID 22335898, 2012). "Increased expression of TRPV1 in DRGs is evident in this model, as well as in a trinitrobenzenesulfonic acid (TNBS) colitis model, suggesting that TRPV1 up-regulation may be a mechanism by which the effect of a TRPV1 antagonist becomes manifest." (PMID 24288041, 2011). "Another study has suggested that SP release from sensory neurons expressing TRPV1 or TRPA1 may contribute to the progression of DSS-induced colitis, wherein CGRP provides protection against colon inflammation independently of TRPV1 and TRPA1 expression on sensory neurons." (PMID 38731999, 2024). "TRPV-1 is involved in several inflammatory diseases, such as in inflammatory bowel disease (IBD), cutaneous neurogenic inflammation, brain inflammation, allergic asthma, cough, colitis, arthritis, hypersensitivity, chronic obstructive pulmonary disease (COPD), and autoimmune diseases." (PMID 36613152, 2023). "Besides TRPA1/TRPV1, TRPM8 is also functionally expressed by the colon-innervating DRG neurons and TRPM8 expression is upregulated in inflamed colon samples from both human and mouse models of DSS- and TNBS-induced colitis." (PMID 36459135, 2023). "In DSS-induced colitis model, the TRPV1/CGRP-positive nerve fiber density increases in the distal colon wall and TRPV1 activation-induced release of CGRP/SP from the distal colon is greater than that from the proximal colon, which is further enhanced in the setting of colitis." (PMID 36459135, 2023). "Therefore, pain control by suppressing TRPV1 and TRPA1 proteins could be a promising target in colitis management." (PMID 35269566, 2022). "Colitis rats induced by 5% DSS and supplemented with 100 mg LBP/kg bw for 4 weeks reduces serum lipid peroxidation substance MDA levels, colonic TNF-α, serum IL-6 levels, and the expression of pain signaling proteins TRPV1 and TRPA1 in the colon, and enhance serum antioxidative CAT activity." (PMID 35269566, 2022). "However, upregulation of TRPV1 could also be a consequence of inflammation, e.g. in TNBS-induced colitis, although CS on its own only boosts cytokine production without any histological damage." (PMID 32760089, 2020). "Taken together, these data demonstrate substantial inflammatory changes in the distal colon during acute colitis in both WT and TRPV1−/− groups suggesting that the lack of TRPV1 receptors does not prevent the colon from the development of acute inflammatory reaction." (PMID 23305398, 2013). "High-threshold splanchnic afferents innervating the mesentery and serosa of the colon fail to be sensitized in rats with dextran sulfate sodium (DSS)-induced colitis, yet the response of these fibers to mechanical probing is attenuated by a TRPV1 blocker in inflammation but not health." (PMID 21420431, 2011). "As chronic silencing of TRPV1+ afferents was able to prevent VHS and microglial activation in the spinal cord, we next investigated whether TRPV1+ neurons activation was sufficient to trigger microglial activation associated with VHS in the absence of colitis." (PMID 34954381, 2022).
colitis (continued). "However, the contribution of TRPA1 to different types of inflammation may not be as prevalent as that of TRPV1, with recent reports suggesting the severity of colitis induced by TNBS is unaffected by TRPA1 deletion." (PMID 27713376, 2010). "Wild-type mice with oil of mustard (OM)-induced colitis have been reported to show an increase in levels of neuronal TRPA1, while TRPV1 activation in the colon was not significant." (PMID 38731999, 2024). "A recent paper has shown that both TRPV1 and TRPA1 are pro-inflammatory in nature and act in a similar manner (not antagonistic manner as claimed) in DSS-induced colitis using TRPA1 and TRPV1 knockout mice." (PMID 31488616, 2019). "Bertin and co-workers proposed non-neuronal TRPV1 and TRPA1-mediated proinflammatory mechanisms in colitis." (PMID 30935063, 2019). "No significant upregulation of colonic Trpv1 mRNA was detected in DSS treated WT mice, similarly as in mustard oil (MO) induced colitis." (PMID 25265225, 2014).
breast carcinoma (64 papers, 2013 to 2025). "The level of sensory innervation and the expression of sensory neuronal markers like TRPV1 and Nav1.8 have been linked to poor prognosis in breast cancer." (PMID 38433844, 2024). "Similarly, a peptide mimicking the γ-aminobutyric acid type A (GABAA) receptor-associated protein (GABARAP) which interacts with TRPV1 has been proposed as a good candidate to promote TRPV1-associated suppression of breast cancer progression." (PMID 35565390, 2022). "The decrease of TRPV1 expression in renal cell carcinoma was significantly associated with tumor Fuhrman grades and histopathological subtypes, while the intracellular aggregated TRPV1 was associated with lower survival in breast cancer patients." (PMID 31183372, 2019). "Subcellular localization of TRPV1 carries potential clinical meaning: “classical” (plasma membrane/cytoplasmic) distribution correlates with better prognosis, whereas “non-classical” ER/Golgi-centric aggregates associate with poorer survival in breast cancer specimens." (PMID 41303593, 2025). "In fact, MMPs are also involved in the immune response, and perhaps it plays a role in TRPV1’s anti-breast cancer metastasis through the neuroimmune pathway, which needs to be further investigated." (PMID 40007993, 2025). "Activation of TRPV1 by capsaicin leads to strong calcium increases and induces apoptosis in breast cancer cells and glioma cells." (PMID 40013655, 2025). "For instance, vagal visceral afferent nerve endings express TRPV1: their activation decreased breast cancer metastasis and reduced pro-inflammatory cytokines, all while upregulating the release of SP." (PMID 39940997, 2025). "In vitro, TRPV1 expression has been demonstrated in various neoplasms, including human breast carcinoma, glioma, papillary thyroid carcinoma, and prostate carcinoma." (PMID 40804975, 2025). "Activation of TRPV1 by capsaicin leads to strong calcium increases and induces apoptosis n breast cancer cells and glioma cells." (PMID 40013655, 2025). "The balance between the expression of TRPV1 and the triggered calcium influx into the cells are important factors controlling breast cancer cell proliferation." (PMID 38791297, 2024). "It has been shown that capsaicin induces high TRPV1 expression and apoptosis in breast cancer cell lines." (PMID 38791297, 2024). "Confusingly, in mice, the genetic inactivation of Trpv1 prevented both bone colonization and lung metastasis formation by 4T1 breast cancer cells." (PMID 38339399, 2024). "The reported expression of TRPV1 varies among different breast cancer subtypes: the highest expression was observed in TNBC, followed by the luminal and basal-like subtypes." (PMID 38734935, 2024). "The expression of TRPV1 has been observed in breast cancer, prostate carcinoma human pancreatic cancer, and tongue squamous cell carcinoma." (PMID 38612571, 2024). "The combined use of DDP and selenium can induce oxidative stress and increase Ca2+ concentration in breast cancer cells MCF-7 by regulating TRPV1 channels, thereby exerting anticancer effects." (PMID 39132151, 2024). "Weberet al. reported that TRPV1 expression is significantly greater in breast cancer tissues than in paracancerous tissues." (PMID 38734935, 2024). "The activation of TRPV1 significantly inhibits the growth of breast cancer cells and induces apoptosis and necrosis." (PMID 38706904, 2024). "Activated TRPV1 induces breast cancer cell apoptosis and inhibits cell proliferation and migration, providing a new approach for the development of treatment strategies." (PMID 38734935, 2024). "In breast cancer cell lines, TRPV1 protein was found with two distinct patterns of expression that are correlated to estrogen receptor expression." (PMID 39407657, 2024). "Of note, TRPV1 expression in breast cancer cell lines and animal models has a large body of literature which is beyond the scope of this review." (PMID 37240443, 2023).